VIM (vimentin)
Diseases named in the same sentence as VIM in open-access papers (continued):
Sharing a sentence is not in itself a finding about the gene and the disease.
melanoma (continued). "The gene expression profile of AXL, which is at the top of the list of migration-related gene, was remarkably similar to that of the mesenchymal marker genes VIM and SNAI2 (Slug), with some exceptions, most notably by melanoma lines that strongly expressed VIM and SNAI2, but not AXL." (PMID 22570691, 2012). "Interestingly,statistical analyses revealed that in primary melanoma, simultaneousexpression occurs more frequently when compared to the metastaticmodels (88% vs 60%) but any specific correlation was not identifiedamong tested subgroups including CD44 + vimentin, CD44 + MCAM, andvimentin + MCAM." (PMID 40621031, 2025). "Furthermore, female WM266-4 and M21 melanoma cells exposed to acidosis do not modify their proliferation, N-cadherin, and vimentin expression, while male HS294t and SKMEL2 cells show a reduction in cell growth and a significant increase of N-cadherin and vimentin." (PMID 36499700, 2022).
glioma (216 papers, 2005 to 2026). A benign or malignant brain and spinal cord tumor that arises from glial cells (astrocytes, oligodendrocytes, ependymal cells). "Vimentin expression, when present in gliomas, is often associated with a more aggressive, therapy-resistant phenotype." (PMID 40937216, 2025). "High vimentin expression is often associated with more aggressive gliomas, where tumor cells exhibit increased motility and capacity to invade healthy neural structures." (PMID 40937216, 2025). "Vimentin, typically associated with mesenchymal transition, is highly expressed in DMGs and high-grade gliomas, reflecting aggressive behavior and invasiveness." (PMID 40937216, 2025). "We have previously confirmed the presence of glioma stem-like cells, cells expressed neural stem cell markers, nestin and vimentin which are regarded as tumorigenic and associated with the heterogeneity in GBM." (PMID 40569470, 2025). "Vimentin, synaptophysin, and H3K27me expression patterns offer practical, cost-effective surrogate tools to enhance diagnostic accuracy in glioma classification." (PMID 40937216, 2025). "Vimentin's association with aggressive, mesenchymal-like transformation supports its utility in identifying high-grade gliomas such as DMGs, while synaptophysin expression points toward neuronal differentiation, favoring a diagnosis of oligodendroglioma." (PMID 40937216, 2025). "Given its role in tumor biology, vimentin has gained significant attention as a diagnostic and prognostic marker in gliomas." (PMID 40937216, 2025). "This review explores the diagnostic significance of vimentin, synaptophysin, and H3K27me, highlighting their role in glioma classification and their potential utility in differentiating oligodendrogliomas from DMGs." (PMID 40937216, 2025). "At the same time, we collected the immunohistochemical and genetic detection results of glioma patient samples, including Vimentin, S-100, GFAP, SYN, EMA, CD34, Ki67, IDH mutation, MEMG methylation and 1p/19q lost and other information." (PMID 36831736, 2023). "Reduction of VIME/VIM levels by P4 represents a beneficial effect, as high VIME/VIM expression correlates with a high grade in gliomas while low vimentin levels associated with better survival and temozolomide response in GBM." (PMID 32590878, 2020). "Enhanced levels of transcripts encoding Sox2, Musashi 1, Nestin and Vimentin were observed in the glioma cultures assayed and in neural stem cells as compared to adult cortical tissues." (PMID 21297991, 2011). "Other CNS tumors, such as ependymomas, meningiomas, and choroid plexus tumors, may also express vimentin, though its diagnostic significance in these tumors is limited compared to glioma." (PMID 40937216, 2025). "Vimentin expression patterns across glioma subtypes and their diagnostic significance." (PMID 40937216, 2025). "EGFR and VIM are markers previously associated with proliferative glioma cells." (PMID 38275289, 2024). "In this statistical analysis, it was found that in the CNS WHO grade 4 glioma patient group, the expression of Vimentin protein may be associated with the presence of tumor MVD (χ2=3.504, P=0.070)." (PMID 39668822, 2024). "Finally, we investigated the association between the survival rate for glioma patients and vimentin and/or NgR gene expression by using survival data from TCGA." (PMID 31649250, 2019). "Mechanistically, inhibition of PLOD2 inactivated PI3K/AKT signaling pathway and thus regulated the expression of its downstream epithelial–mesenchymal transition (EMT)-associated regulators, including E-cadherin, vimentin, N-cadherin, β-catenin, snail and slug in glioma cells." (PMID 28410212, 2017). "This, along with Notch-mediated overexpression of SNAIL, ZEB1, and vimentin, further enhances glioma cell invasion and migration." (PMID 41141394, 2026). "The level of vimentin expression varies across different glioma subtypes, providing important insights into their biological behavior and diagnostic classification." (PMID 40937216, 2025).
glioma (continued). "Despite the promising clinical applications of vimentin, synaptophysin, and H3K27me, there remain several limitations and gaps in research that must be addressed to further optimize their use in glioma diagnostics and treatment planning." (PMID 40937216, 2025). "Vimentin, a mesenchymal cytoskeletal protein, is upregulated in more aggressive gliomas and is typically expressed in DMGs, reflecting their high invasiveness." (PMID 40937216, 2025). "In the absence of comprehensive molecular testing, immunohistochemical markers such as vimentin, synaptophysin, and H3K27me serve as valuable surrogate tools to differentiate between these glioma subtypes." (PMID 40937216, 2025). "In high-grade gliomas, strong vimentin expression correlates with epithelial-to-mesenchymal transition (EMT), increased tumor invasiveness, and poor treatment response." (PMID 40937216, 2025). "To further investigate the relationship between LDH isoenzymes and PMT in glioma, we analyzed protein expression levels of VIM (mesenchymal marker) and OLIG2 (proneural marker) through western blotting." (PMID 39895794, 2025). "First, vimentin enhances tumor invasion and migration, enabling glioma cells to infiltrate the surrounding brain tissue." (PMID 40937216, 2025). "In neuro-oncology, vimentin expression is often correlated with tumor aggressiveness, particularly in high-grade gliomas." (PMID 40937216, 2025). "For example, Yang and Wang found that VPA inhibited the invasion and metastasis of glioma cells through upregulation of E‐cadherin and downregulation of vimentin and N‐cadherin." (PMID 40650414, 2025). "AGR2’s co-expression with stemness markers such as Nestin and Vimentin highlights its role in maintaining glioma stem cell survival and contributing to recurrence, positioning AGR2 as a potential diagnostic and therapeutic target." (PMID 41179304, 2025). "Apart from these, WB also identified despite knockdown of NCAPH, overexpression of PIK3CA decreased E-Ca expression along with increase in the Snail, vimentin, and N-Ca expression in glioma cells." (PMID 38587786, 2025). "The primary search string used was: ("vimentin" OR "synaptophysin" OR "H3K27me3" OR "H3K27M") AND ("oligodendroglioma" OR "diffuse midline glioma" OR "glioma classification" OR "brain tumor diagnosis")." (PMID 40937216, 2025). "Given its differential expression across glioma subtypes, vimentin serves as an important surrogate marker in tumor classification, particularly when molecular testing is unavailable or inconclusive." (PMID 40937216, 2025). "Consistent with the cellular behaviors, molecular changes related to mesenchymal transition were also reversed, characterized by decreased expression of Vimentin and N-cadherin, and increased expression of E-cadherin in glioma cells when GPR65 was inhibited." (PMID 38576043, 2024). "The expression levels of tumor invasion and EMT‐related molecules, including MMP2, N‐cadherin, Snail, and Vimentin, were significantly decreased in the knockdown glioma groups." (PMID 37545464, 2024). "These transcription factors can enhance the expression of Vimentin, thereby promoting the migration and invasion of glioma cells." (PMID 39668822, 2024). "DYRK2 is expressed in human tumors and can suppress glioma cell migration, affecting E-cadherin and vimentin expression in the PI3K/AKT/GSK3β signaling pathway." (PMID 38584840, 2024). "We first performed antigen retrieval and stained high-grade glioma and normal hippocampus with anti-vimentin or anti-MAP/anti-GFAP." (PMID 38295184, 2024). "Our prior experiments using glioma tissues demonstrated that post-expansion staining increases the intensity, continuity, and number of structures stained for vimentin, Iba1 and GFAP vs. pre-expansion staining." (PMID 38295184, 2024). "CF-ME treatment decreased N-cadherin and vimentin expression in glioma cells while increasing E-cadherin levels." (PMID 39408228, 2024).
glioma (continued). "Future studies are needed to confirm menin’s interaction with GFAP and vimentin in additional glioma cell lines and patient samples, as well as to investigate the effects of menin on glioma cell migration and invasion." (PMID 39336822, 2024). "Regulation of Vimentin by c-Jun in glioma cells was further confirmed with the use of a JNK inhibitor, which decreases phosphorylated c-Jun levels and subsequently Vimentin levels." (PMID 36850002, 2023). "In a recently described extremely rare epileptogenic angiocentric glioma, there are high levels of vimentin expression, epithelial membrane antigen (EMA) and glial fibrillary acidic protein (GFAP)." (PMID 38067243, 2023). "Conditioned media from GAMs significantly upregulated N-Cadherin and Vimentin, whereas downregulated E-Cadherin’s expression of RNA and protein in glioma cells." (PMID 36969175, 2023). "Because the glioma stem cell niche is associated with overexpression of several proteins, including OCT4, Nestin, Vimentin, and Sox-2, we sought to visualize HML-2 expression in situ with multiplex immunofluorescence." (PMID 37395282, 2023). "Vimentin is highly expressed in glioma cells and likely plays a prominent role in progression and resistance to cancer therapy, and it is also associated with a negative prognosis for glioma patients." (PMID 38067243, 2023). "Pritumumab is another anti-vimentin monoclonal antibody used in glioma patients that binds to malignant cells expressing vimentin at their surface and is able to distinguish physiological and malignant vimentin." (PMID 37475865, 2023). "DNA–protein complexes with VIM gene promoter probe were more efficiently formed in nuclear extracts from GBM-derived than in benign GII glioma cells." (PMID 36850002, 2023). "We found HML-2 expression in the same cells and tissues that expressed stem cell markers, namely OCT4, Nestin, Vimentin, and Sox2 in patients with high-grade glioma." (PMID 37395282, 2023). "We also demonstrated using immunofluorescence staining that silencing cNDC80 dramatically decreased the expression levels of N-cadherin and Vimentin in transduced glioma cells." (PMID 36635757, 2023). "The levels of vimentin and N-cadherin were remarkably increased in glioma cells transfected with sh-circRNA_103239, where the expression of E-cadherin was down-regulated." (PMID 38021156, 2023). "Recently, a pro-angiogenic and pro-inflammatory role of vimentin was discovered, suggesting that vimentin has various functions in tumours, including glioma progression." (PMID 36765531, 2023). "Sumoylation of vimentin by Protein Inhibitor of Activated STAT3 (PIAS3) inhibits glioma cell migration while acetylation of vimentin intermediate filaments at K120 b SIRT5 increases metastasis in hepatocellular carcinoma." (PMID 35573702, 2022). "In this study, we showed that paeoniflorin inhibited EMT process through downregulating the mesenchymal markers like N-cadherin, snail and vimentin, which has been reported highly expressed in glioma and were closely related to the poor prognosis." (PMID 35957872, 2022). "Western blotting also showed that overexpression of STAT3 reduced the expression of E-Ca and increase the expression of N-Ca, vimentin, and Snail in glioma cells in response to TMEM158 knockdown." (PMID 34992215, 2022). "As a mesenchymal marker, the downregulation of vimentin inhibited the migration and invasion ability of glioma cells." (PMID 34953010, 2022). "Then, the expression of E-cadherin in the siRNA1 and siRNA2 groups was significantly upregulated compared to controls, while N-cadherin and vimentin were downregulated in glioma cells." (PMID 35571491, 2022). "MiR-155-5p overexpression results in the upregulation of EMT markers, including TWIST2, vimentin and N-cadherin, suggesting that miR-155-5p promotes mesenchymal transition in glioma cells." (PMID 35986010, 2022).
glioma (continued). "In contrast, downregulating TMEM158 in glioma cells significantly increased the expression of E-Ca and decreased the expression of N-Ca, vimentin, and Snail." (PMID 34992215, 2022). "Western blot was utilized to evaluate ZEB2 expression and epithelial-mesenchymal transition (EMT-)-related proteins (E-cadherin, N-cadherin, as well as Vimentin) in glioma cells." (PMID 36193069, 2022). "E-Ca was downregulated in TMEM158-overexpressed U87MG, U251MG, and TJ905 glioma cells, while N-Ca, vimentin, and Snail were upregulated." (PMID 34992215, 2022). "Several known glioma markers were identified through this analysis such as Vimentin, Nestin, BCAT1, and S100A1." (PMID 35526077, 2022). "Western blot analysis also demonstrated that the protein levels of Vimentin and N-cadherin were reduced, but that of E-cadherin was increased in glioma xenografts derived from U-87 MG-pLV-LASS2 cells compared with those derived from U-87 MG-pLV cells." (PMID 35517425, 2022). "In glioma cells and specimens of surgical resection, EMT-associated proteins, including vimentin, N-cadherin, and E-cadherin as an invasive marker, have been known to show a marked elevation of expression." (PMID 35448004, 2022). "Immunofluorescence images of vimentin revealed that silencing MEOX2 resulted in significant downregulation of vimentin in glioma cells." (PMID 35436995, 2022). "Because E-cadherin is expressed at very low levels in LGG cells, the levels of two common EMT markers (N-cadherin and Vimentin) were detected to analyze the EMT process in glioma." (PMID 34281539, 2021). "Activated NF-κB can mediate the activation of STAT3, CEBPB, and TAZ by upregulating the expression of CD44, vimentin, and N-cadherin, thereby promoting the invasion, angiogenesis, and therapeutic resistance of glioma." (PMID 34246306, 2021). "In glioma cells, the mRNA and protein expression of E-cadherin was enhanced, while Vimentin was reduced by the inhibition of ZNF609." (PMID 34520391, 2021). "Our results suggest that apart from regulating Caprin2 expression, lncRNA-MUF modulates the expression of several genes involved in the TGF-β pathway in glioma cells (vimentin, CTGF, c-Myc, and Snail1) with Snail1 as one of the primary targets." (PMID 35223453, 2021). "The EMT-like process of glioma tumor cells included the reduction of E-cadherin in addition to the rise of N-cadherin and vimentin." (PMID 34868922, 2021). "Several reports have demonstrated that the EMT process can be triggered, accompanied by the overexpression of vimentin and low expression of E-cadherin, and is involved in glioma cell migration and invasion." (PMID 33628783, 2021). "Consistently, we found that high CD68 and VIM expression correlate with poor prognosis of glioma patients." (PMID 34805184, 2021). "Collectively, LBX2-AS1 and miR-491-5p regulated the expression of N-cadherin, E-cadherin and Vimentin in glioma cells by the LIF/STAT3 axis." (PMID 34729101, 2021). "Ropivacaine treatment upregulates E-cadherin expression and represses vimentin expression in glioma cells, resulting in metastasis inhibition." (PMID 34696683, 2021). "Assuming that CALU played a vital role in regulating glioma EMT, we investigated the association between CALU and EMT markers, including N-cadherin, E-cadherin, snail, slug, and vimentin." (PMID 33623713, 2021). "We have found that overexpression of miR-1298-3p downregulates the levels of NID1 and vimentin, and upregulates the level of E-cadherin in glioma cells, indicating that overexpression of miR-1298-3p inhibits glioma cell invasion." (PMID 32355035, 2020). "CD73 downregulation decreased glioma cell migration and invasion by reducing metalloproteinase-2 and vimentin expression and reduced cell proliferation." (PMID 32443824, 2020).